INS (insulin)
Diseases named in the same sentence as INS in open-access papers (continued):
Sharing a sentence is not in itself a finding about the gene and the disease.
Obesity (continued). "Compared with adolescents without obesity, adolescents with obesity have increased levels of circulating free fatty acids, which reduce insulin sensitivity, potentially contributing to impaired insulin secretion." (PMID 32348264, 2020). "Previous reports also have shown that inflammation could result from obesity, which is attributed to overexpression of MCP-1, and consequently, generating defective insulin secretion, insulin resistance, and interfering with other processes of energy homeostasis as well." (PMID 32069832, 2020). "At 4 months of age, db/db mice continued displaying dramatic obesity (+60% in body weight) and hyperinsulinemia (+5.9-fold in nonfasted blood insulin); however, at this stage, hyperglycemia was milder compared with its peak at 2 months of age (+1.9-fold in nonfasted blood glucose)." (PMID 33148881, 2020). "Several data, likewise, have shown that a deletion or a mutation of Opa1, with consequent impairment of the mitochondrial fusion process, can influence, in a negative manner, the insulin-stimulated mitochondrial energy metabolism, involved in the regulation of obesity and diabetes." (PMID 32414136, 2020). "The effect of EPA on obesity may be partly mediated by binding to G protein-coupled receptor 120 (GPR120) present in adipocytes and adipocyte tissue macrophages (ATMs), thus regulating adipogenesis, glucose uptake, inflammation and insulin sensitivity." (PMID 32992508, 2020). "The change in adiponectin level was not significantly correlated with the change in insulin sensitivity or the improvement in obesity parameters; this could be explained by the short period of the intervention." (PMID 33259020, 2020). "The inability of our mice to maintain their circulating concentrations of glucose and insulin within a healthy range is a critical step in the pathway from obesity to chronic diseases; however, impaired glucose metabolism can develop in the absence of obesity." (PMID 32260528, 2020). "Oral administration of scopolin in an OVX-induced obesity mouse model revealed that scopolin prevented OVX-induced weight gain, an increase in body fat percentage, hepatic steatosis, and an increase in epididymal fat by downregulating serum leptin and insulin levels." (PMID 33218042, 2020). "In obesity, omentin circulating and expression levels in VAT are decreased, correlating positively with plasma adiponectin and high-density lipoprotein (HDL) levels and negatively with the waist circumference, BMI, leptin and fasting insulin levels, and it is considered a marker of leanness." (PMID 33081064, 2020). "In addition, IL32 has been shown to have inflammatory properties in human obesity and have a negative impact on insulin sensitivity and myogenesis, while TNFRSF12/FN14 has been implicated in various muscle wasting diseases and metabolic dysfunction." (PMID 32624006, 2020). "However, differences in obesity development related to the different fatty acid profiles in the diets did not directly translate into differences in insulin sensitivity and glucose tolerance." (PMID 33022997, 2020). "These cellular mechanisms underscore the potentiating effects of fructose on the β-cell response at intermediate physiological glucose concentrations, raising insulin secretion to non-physiological levels that might favor obesity." (PMID 32492936, 2020). "Analysis of metabolic parameters showed lower insulin (p < 0.05), HOMA-IR (p < 0.05), triglycerides levels (p < 0.05) and liver transaminases (AST, and ALT p < 0.05 for both) in PWS than controls with common obesity, suggestive of a healthier metabolic profile in the former." (PMID 31974460, 2020). "Collectively, these data suggest that spinach-derived thylakoid along with calorie-restrictive diet may be a promising adjunct therapy without any side effects for the management of obesity and insulin sensitivity, in OCP treated obese women with PCOS." (PMID 32782010, 2020).
Obesity (continued). "Interestingly, our results are consistent with those from human study in which apple intake in obesity contest, reduces serum triacylglycerols and total cholesterol without modification in glucose:insulin ratio." (PMID 33198144, 2020). "Using peripheral blood mononuclear cells as a source of DNA, another epigenome-wide study compared insulin-resistant versus insulin-sensitive non-diabetic women with obesity, classified according to hyperinsulinemic euglycemic clamps, without finding differences by PPARGC1A methylation status." (PMID 32933059, 2020). "Furthermore, obesity induces chronic low-grade inflammation, which also negatively impacts insulin sensitivity." (PMID 32397116, 2020). "However, women with obesity or a history of GDM enter pregnancy with pre-existing IR that worsens with advancing gestation; overweight/obese women have decreased insulin sensitivity as compared with lean women, although both groups have a similar 50% decrease of insulin sensitivity during gestation." (PMID 33424775, 2020). "The risk increase for death may, as an example, be mediated by unhealthy fat distribution, independent of insulin levels, that is associated with higher GIP release, or by promotion of obesity." (PMID 31974732, 2020). "The origin of obesity in cancer survivors is not fully explained, but likely includes physical inactivity, damage to the hypothalamus and endocrine organs, and resistance to insulin and leptin, among others." (PMID 32153654, 2020). "A very low carbohydrate diet (VLCD) may be a means of promoting fat loss from the visceral cavity and skeletal muscle, without compromising lean mass, and improve insulin sensitivity in aging adults with obesity." (PMID 32817749, 2020). "However, in the matched cohort, except for age, obesity, eye disease, insulin and sulfonylurea, all other variables were not different significantly." (PMID 33194743, 2020). "In that study, the difference in insulin sensitivity between the sedentary and endurance trained older adults was ~20% and the two groups showed identical ceramide content and composition suggesting a discordant relationship between insulin sensitivity and ceramides in the absence of obesity." (PMID 32098447, 2020). "Moreover, obesity increased plasma insulin with exercise training decreasing glucose but not insulin." (PMID 32230849, 2020). "HFD-fed mice developed severe obesity (+71% in body weight), hyperinsulinemia (+2.9-fold in nonfasted serum insulin), and hypertriglyceridemia (+53% in nonfasted serum triacylglyceride, TAG) but did not display basal hyperglycemia (no significant changes in nonfasted blood glucose)." (PMID 33148881, 2020). "Thus, abnormalities of insulin clearance may induce IR and then the occurrence of various pathological conditions including T2DM and severe obesity." (PMID 32414367, 2020). "Contrary to our expectations regarding RS action and suppression of appetite, the ad libitum feeding strategy resulted in obesity development and increasing insulin and glucose levels over time in both groups, without changes in dyslipidemia markers between fructose and HiMaize." (PMID 33198236, 2020). "In addition, it is reported that the deterioration of glucose tolerance in healthy elderly subjects is due to a decrease in insulin secretion and can be explained by the degree of obesity rather than age." (PMID 32505171, 2020). "Third, we could not analyze blood parameters related to obesity and metabolic dysfunction such as adiponectin, leptin, and insulin levels because of lack of data." (PMID 32365676, 2020). "Skeletal muscle is the primary target organ of insulin‐mediated glucose disposal, and therefore, sarcopenia itself, independent of obesity, may aggravate IR." (PMID 32638541, 2020).
Obesity (continued). "The intervention aimed at children suffering from obesity and their mothers modified some dietary habits and behaviors at home and improved insulin levels and HOMA-IR in a context where they were not given a specific diet as a treatment nor did they receive intervention on physical activity." (PMID 32795294, 2020). "Studies have shown that obesity or a long-term high-fat diet leads to an increase in the levels of various inflammatory factors including TNF-α, IL-1, IL-6, and MCP-1 and decreases in the anti-inflammatory factors such as IL-10 and IL-4 in insulin target tissues in insulin-resistant individuals." (PMID 33013197, 2020). "HFD-fed wild-type C3H/HeN mice colonized with B29 showed markedly degenerated hepatocytes, a significant increase in NAFLD activity score, obesity, and an insulin-resistant phenotype, unlike the corresponding HFD-fed GF control mice, after 15 weeks of HFD treatment." (PMID 32019793, 2020). "For example, HFD feeding to FFAR2 KO mice shows improved oral glucose tolerance test (OGTT) and insulin sensitivity along with lower fat mass and increased lean mass compared to wild type (WT) mice, indicating that the deletion of FFAR2 protects HFD-induced obesity/T2D." (PMID 32521775, 2020). "Besides, in elderly non-diabetic subjects with overweight or obesity, serum ATX (ENPP2 in rats) associated with the measures of glucose homeostasis and is an independent predictor of insulin sensitivity." (PMID 32256445, 2020). "In male C57BL/6 J mice fed a 10 week long HFD to induce obesity, restricting methionine increases plasmatic but also skeletal muscle adiponectin, downregulates the mTOR pathway and upregulates MAPK and IRS-1 mRNA levels in gastrocnemius muscle, leading to an improvement in insulin sensitivity." (PMID 32827096, 2020). "Intriguingly, no changes or even increases in insulin signaling activation may also characterize early obesity stages in a time-dependent fashion." (PMID 33158222, 2020). "Interestingly, BMAT expansion accompanying obesity has no adverse effects on insulin sensitivity in marrow adipocytes, unlike peripheral white adipocytes, which manifested impaired insulin sensitivity [18••]." (PMID 31749085, 2019). "However, another study showed that TLR3 deficiency in mice does not significantly influence HFD-induced obesity and system insulin sensitivity or inflammation." (PMID 31582899, 2019). "However, molecular metabolic effects on the glucose tolerance and insulin sensitivity of these newer beta-blockers in obesity have not been investigated." (PMID 31682617, 2019). "In this study two obese ponies were insulin-dysregulated, while two were not, therefore a greater sample size of obese ponies with a range of cresty neck scores would be required to further elucidate the role of generalised obesity in EMS." (PMID 31339945, 2019). "As already stated, obesity and metabolic syndrome are characterized by chronic inflammation and high levels of cytokines that are known to impact on Leydig cell steroidogenesis and T levels either directly interfering with the HPT axis or indirectly altering the insulin transduction pathway." (PMID 31817436, 2019). "Accordingly, in our study, we induced cognitive dysfunction through obesity that resulted from a high-fat diet (HFD) and investigated whether the decline in cognitive function could be improved with exercise by examining insulin signaling pathways and neuroplasticity in the hippocampus." (PMID 31311133, 2019). "Taken together, these results indicated that although the body weight of rats increased after Ad36 infection, the blood glucose and blood triglyceride levels did not increase, insulin sensitivity was normal, and lipid ectopic deposition did not occur, which were unlike high-fat induced obesity." (PMID 30902099, 2019).
Obesity (continued). "The present study findings are complementary to prior work, showing that FGF21 administration can improve glucose tolerance and insulin sensitivity in diabetic rodents as well as a prior study showing that transgenic overexpression of FGF21 is protective against HFD-induced obesity in mice." (PMID 31121855, 2019). "During obesity, activation of inflammatory, and stress kinases such as JNK and IKK is responsible for an uncontrolled phosphorylation of IRS on inhibitory serine sites resulting in a decrease in IRS tyrosine phosphorylation and a desensitization of insulin signaling." (PMID 31738794, 2019). "Obesity drives an excessive lipid accumulation in adipocytes, which provokes immune cells infiltration, fibrosis (an excess of deposition of ECM components such as collagens, elastin, and fibronectin) and inflammation, considered a consequence of local hypoxia, and ultimately insulin resistance." (PMID 31581657, 2019). "Finally, recent findings demonstrated that adipose-tissue-resident Tregs accumulate in visceral depots as a function of age, but not obesity, and selective depletion of adipose-resident Tregs in these aged animals enhanced adipose tissue insulin sensitivity." (PMID 31443389, 2019). "Moreover, a cross-sectional cohort study on 1,292 healthy non-diabetic men demonstrated a negative correlation between TT and insulin levels, maintained after adjustment for age and obesity." (PMID 31402895, 2019). "Moreover, the decrease of fasting insulin was not statistically significant in simple obesity, but in T2DM with obesity, and heterogeneity still existed (MD, − 2.92; 95% CI, − 4.49- -0.74; P = 0.006; I2 = 83%)." (PMID 31760943, 2019). "Despite the evidence linking anti-TNF strategies with the improvement of insulin sensitivity, it is not known how the selective neutralization of solTNF signaling can impact the deleterious metabolic-immune interactions present in obesity that affects IR." (PMID 31892368, 2019). "However, the Ip6k3−/− mouse is not resistant to obesity, and serum insulin and glucose levels of Ip6k2−/− mice are normal." (PMID 31186349, 2019). "Interestingly, basal norepinephrine was well-correlated with the plasma leptin, but not plasma insulin in obesity." (PMID 31682617, 2019). "Conversely, TNF-α was positively related, and IL-6, leptin, insulin, total n-6, n-3 and n-6/n-3 PUFAs in whey breastmilk were negatively correlated to several infant growth measures in offspring of women without overweight or obesity." (PMID 31141526, 2019). "However, HFD-induced obesity did not impair insulin sensitivity in adipocytic progenitors of BM, as BM shows normal levels of pAKT as well as insulin signaling genes after insulin stimulation." (PMID 30800100, 2019). "We found that Tmem127 actions on insulin are independent of obesity." (PMID 31624249, 2019). "In a mouse model of diet-induced obesity, this study determined if two exercise prescriptions with equivalent time and distance covered, [constant-moderate endurance (END) and high intensity interval training (HIIT)], exert differential metabolic benefits on insulin sensitive tissues." (PMID 31105582, 2019). "Whether trans-PAO has an impact on increasing insulin sensitivity requires further investigation in a diet-induced obesity mouse model as the Apoe−/- mice do not represent a good model to study insulin resistance." (PMID 31422082, 2019). "The aim of the present study was to assess the effect of moderate weight loss during low-calorie diet on insulin sensitivity, AT and peripheral blood mononuclear cells (PBMC) inflammatory gene expression in young subjects with obesity without concomitant diseases." (PMID 29737494, 2018). "Furthermore, Cited4 inactivation resulted in compromised therapeutic insulin sensitization in female but not male mice when rosiglitazone was administered in the context of diet‐induced obesity." (PMID 29973382, 2018).
Obesity (continued). "Besides preventing a decrease in irisin levels, chronic CT improved some metabolic parameters such as total cholesterol, LDL cholesterol, glucose, insulin, and the homeostatic model assessment of insulin resistance (HOMA-IR), reinforcing the importance of physical exercise in treating obesity." (PMID 29643769, 2018). "The first study that established the reframing of obesity as an inflammatory condition demonstrated the detrimental effect of tumor necrosis factor alpha (TNF-α), an inflammatory mediator secreted by adipose tissues, on insulin resistance in many animal models of obesity." (PMID 29951059, 2018). "The role of leptin on mitochondrial function and insulin sensitivity in hypothalamus is dependent on mitochondrial HSP60, suggesting that the hypothalamic mitochondrial chaperone system has an important effect on systemic energy homeostasis in obesity and metabolic diseases." (PMID 30307158, 2018). "Given the detrimental effects of body fat and obesity on insulin sensitivity, it is not unreasonable to suggest that this premature accumulation of body fat at 6 months of age in our HFO contributed to the loss of earlier whole‐body and skeletal muscle insulin sensitivity at the same age." (PMID 29484855, 2018). "Remarkably, leptin and insulin both require the NSAPP oxide transport chain, suggesting that a defect in this pathway could explain simultaneous resistance to the appetite-suppressing effects of both hormones in obesity." (PMID 29632515, 2018). "Moreover, the pregnant mares belonged to the sport breeds “French Anglo-Arab” and “Selle Français”, that are not known to be prone to develop obesity nor to being insulin resistant (in contrast to ponies)." (PMID 29373573, 2018). "While alterations in insulin and leptin levels have been found in mothers fed hypercaloric diets during pregnancy and lactation, it is important to point out that in our murine model, maternal hypercaloric diet intake does not develop obesity in mothers." (PMID 29991958, 2018). "This protective effect of HFD on retarded weight gain as a result of impaired insulin availability may reflect a specific rodent phenomenon rather than a potential means of preventing obesity in diabetic humans." (PMID 30348168, 2018). "However, because these studies used transgenic animal models that regularly display symptoms of dementia, they were not able to evaluate the effects of obesity-induced insulin dysfunction." (PMID 29673239, 2018). "In many cases obesity is present with insulin dysregulation, yet regional obesity may be absent in some horses with EMS." (PMID 30001422, 2018). "Importantly, obesity‐induced increases in circulating Ly6Chigh monocytes directly correlated with blood insulin levels irrespective of adipose tissue/cell expansion in obese mice." (PMID 30548217, 2018). "It is proposed that even in the absence of clinical diagnosis of IR in OB, the presence of obesity could alter the insulin signaling pathway as measured by AS160 phosphorylation." (PMID 30429793, 2018). "MS is associated with selective BCAA and AAA profile disturbances, which could be part of cardiometabolic disease pathogenesis and derive neither directly from insulin sensitivity impairment, nor obesity or muscle mass." (PMID 29075976, 2017). "Mice with diet-induced obesity show an increased expression of Choline/Ethanolamine Phosphotransferase 1 (CEPT1), the muscle specific knockout of CEPT1 led to improved insulin sensitivity and levels of CEPT1 expression were inversely correlated with insulin sensitivity in obese human subjects." (PMID 28606124, 2017). "Increased ceramide, intramyocellular lipids (IMCLs), diacylglycerol (DAG), and long-chain fatty acyl-CoA levels have been negatively correlated with insulin action, depicting the importance of understanding the link between obesity and the lack of insulin response in skeletal muscle." (PMID 28676863, 2017). "In the absence of PST, animals are insulin sensitive despite obesity." (PMID 28228748, 2017).